TNF (tumor necrosis factor)
Diseases named in the same sentence as TNF in open-access papers (continued):
Sharing a sentence is not in itself a finding about the gene and the disease.
allergic asthma (continued). "It reduced the IL-1β, IL-6, TNF-α, and TGF-β level in OVA-induced allergic asthma both in antibiotic-free and antibiotic-treated mice notably, indicating an anti-inflammatory effect in the OVA-induced allergic asthma model." (PMID 33456673, 2020). "Targeting TNF with etanercept in mild-to-moderate allergic asthma increased the TNFR2 levels but failed to attenuate disease pathologies." (PMID 30473698, 2018). "Furthermore, as the pharmacological inhibition of IL-6 together with TNF has been suggested to be beneficial for patients suffering from severe allergic asthma, it is also interesting to mention that the complete formulation of 2LALERG® also encompasses ULD of TNF-α." (PMID 38541700, 2024). "Interestingly, although injections of TNF/DC induced a mixed Tr1/Th2 response when injected alone, antigen-specific pre-treatment of mice with TNF/DC did not boost subsequent Th2 cell responses such as Leishamania major infection of BALB/c mice or allergic asthma." (PMID 24089996, 2013).
Immunodeficiency (84 papers, 2005 to 2025). Failure of the immune system to protect the body adequately from infection, due to the absence or insufficiency of some component process or substance. "Immunodeficiency induced by CYP treatment has been associated with a decrease in the production of cytokines such as TNF-α and IL-6." (PMID 38474724, 2024). "Ginger polysaccharide has been shown to enhance cytokines IL-2, IL-4, TNF-α, and immunoglobulin Ig-G secretion in the serum of mice, thereby ameliorating immune deficiency." (PMID 38540831, 2024). "Individuals with ESRD have serious immune deficiencies and accumulate a large amount of uremic toxins, which stimulate the body to produce inflammatory factors such as TNF-α, IL-6, and IL-1β, leading to sustained microinflammation reaction." (PMID 37550622, 2023). "Although anti-TNF biologics have been used in clinic, they render several drawbacks, such as patients’ progressive immunodeficiency and loss of response, high cost, and intravenous administration." (PMID 34638561, 2021). "These receptors can trigger the activation of immune cells by two distinct intracellular cascades; the Toll-interleukin 1 pathway and the immune deficiency-TNFα pathway." (PMID 27190105, 2016). "We have mainly analysed the response to TNF-α, which in Drosophila is similar to the immune deficiency (IMD) pathway." (PMID 25510503, 2015). "The results showed that the sodium hyaluronate health drink could improve thymus atrophy, repair spleen cell damage, promote the release of IL-2, IL-6 and TNF-α in serum, restore immune deficiency, and enhance immune function." (PMID 38540831, 2024). "In addition, the results revealed that the patients in the high-risk group were enriched in primary immune deficiency, cell cycle arrest in response, and doxorubicin resistance, and the low-risk group was related to stem-cell downregulated, TNF signaling." (PMID 36837389, 2023). "Its deletion causes immunodeficiency because of B-lymphocytes produce lower levels of immunoglobulins, tumor necrosis factor (TNF) and lymphotoxin, and because of T-lymphocytes produce lower levels of interferon-gamma (IFNγ) and interleukin-12 (IL-12) promoting differentiation to Th2 phenotype." (PMID 33330058, 2020). "Besides, it has been reported that MTX and TNF-α blockers induce lymphadenopathy in RA that are known as “iatrogenic immunodeficiency-associated lymphoproliferative disorders”." (PMID 24839573, 2014). "Therefore, insufficient TNF-α production by T-cells is a potential cause of SCI-induced immunodeficiency." (PMID 24690491, 2014). "Progression to invasive aspergillosis may occur in patients with immune deficiencies caused by glucocorticoids, DMARDs, or TNFα antagonists." (PMID 19886992, 2009). "The association of genes repressed by DN with those induced by TNFα may be interpreted in this context as well, because at least one study suggested poor response to TNFα as one reason for the immune deficiency in T2DM." (PMID 16168088, 2005). "The potential reduction of acetyl-CoA levels in T cells through HBV-induced OXPHOS metabolic reprogramming may inhibit the acetylation levels of target genes, such as IFN-γ and TNF-α, representing a profound mechanism underlying the immune deficiency in exhausted T cells." (PMID 38288308, 2024). "Elevated systemic levels of pro-inflammatory cytokines, such as IL-1, IL-6, and TNF-α, disrupt lymphocyte proliferation, differentiation, and effector responses, thereby driving progressive immunodeficiency." (PMID 40444244, 2025). "Anti-IFNγ and anti-TNFα IgG were also increased, of particular interest because anti-cytokine autoantibodies can lead to immunodeficiency." (PMID 41445737, 2025). "TNF-inhibition is successful in preventing vascular events, while hematopoietic cell transplantation is an option in case of hematological disease and immunodeficiency." (PMID 37179309, 2023).
Immunodeficiency (continued). "In conclusion, aspects of the adaptive immune system, including T-cell and B-cell functions were normal in infants exposed in utero to anti-TNFα, suggesting that a significant secondary immunodeficiency is unlikely." (PMID 36120653, 2022). "In the fruit fly Drosophila melanogaster, recognition of peptidoglycan by the peptidoglycan recognition protein (PGRP) scavenger receptors stimulates the Immune Deficiency (IMD) pathway, similar to that of tumor necrosis factor (TNF) in mammals." (PMID 33194832, 2020). "Disseminated MAC occurs primarily in patients with severe immune deficiency, such as those with advanced HIV infection, hematologic malignancy, or a history of immunosuppressive therapy, such as anti-tumor necrosis factor-α (TNF-α) therapy." (PMID 33101247, 2020). "T. gondii infection induces an imbalance of immune response by causing changes in cytokines such as TNF-α and TGF-β1 in the host, resulting in immune deficiency by breaking homeostasis and interaction of the immune system in the host." (PMID 31075881, 2019). "EBV-driven B-cell LPDs occur in patients who are immunosuppressed due to primary immune deficiency, HIV infection, or organ transplantation or patients who have received other treatments including methotrexate and tumor necrosis factor-α antagonists." (PMID 25834572, 2015). "EBV-driven B-cell LPDs can be age-related or can occur in patients who are immunosuppressed due to primary immune deficiency, HIV infection, organ transplantation, and treatment with methotrexate or tumor necrosis factor-α antagonist for rheumatoid arthritis." (PMID 25834572, 2015). "Further analysis of the relative importance of the presence of anti-IFN-γ antibodies and decreased IL-2 and TNF-α production in HIV-negative immunodeficiency with anti-interferon-γ antibodies and opportunistic intracellular microorganisms is warranted." (PMID 25329064, 2014). "For example, studies of participants with 22q11.2 deletion syndrome (22q11.2DS) (a neurogenetic disorder whose phenotype includes both immunodeficiency and ID/psychotic disorder) found higher levels of inflammatory markers (C-reactive protein, IL-6, IL-10, TNFα) compared with healthy individuals." (PMID 40869088, 2025). "However, our data still suggest a substantial innate immune deficiency in PWH on cART compared with the majority of the participants still having LPS-induced IFN-α and IFN-γ and Poly I:C-iduced IL-6 and TNF-α concentrations below the reference intervals." (PMID 36059528, 2022). "There are also significant similarities between the insect immune deficiency (IMD) pathway which recognizes components of the bacterial cell wall such as peptidoglycan, resulting in the activation of a cascade that ultimately produces AMPs and the mammalian tumor necrosis factor-α (TNF-α) pathway." (PMID 32079502, 2020). "Wild-type bone marrow reconstitution in TNF/LTα deficient mice, that corrects immunodeficiency but not LN formation, could not restore their sensitivity to ECM." (PMID 18612394, 2008). "The expressions of TNF and STAT3 were markedly up-regulated in the CY-induced immunodeficiency after a 14-day treatment with GAC (20 or 40 mg/kg) (p < 0.01)." (PMID 37853057, 2023). "In patients with common variable immunodeficiency, there was a very poor number, if any, of S-specific CD4+ and CD8+ T cells expressing cytokines (IFN-γ, IL-2, and TNF-α)." (PMID 38132279, 2023). "Mice with MAIDS deficient in TNF-a or TNFR1, and therefore deficient in the TNF-a extrinsic apoptotic pathway, were then used to determine the extent that apoptosis might contribute to the retinal tissue pathology of MCMV retinitis during retrovirus-induced immunodeficiency." (PMID 34358000, 2021). "This can be readily observed in patients with inborn or acquired immunodeficiencies, e.g. in HIV-infected patients or patients treated with TNFα-inhibitors." (PMID 28046053, 2017).
Immunodeficiency (continued). "Treatment with anti-TNF is effective for the autoinflammatory and vasculitic components of the disease but does not correct marrow failure or immunodeficiency; and anti-drug antibodies can reduce efficacy over time." (PMID 40555830, 2025). "In this study, it was observed that GAC could increase the expression levels of TNF and STAT3 in mice with CY-induced immunodeficiency." (PMID 37853057, 2023). "This suggests that the TNF and STAT3 genes are likely to be crucial in the development of CY-induced immunodeficiency, and targeting them could be a potential therapeutic approach for GAC in treating immunodeficiency." (PMID 37853057, 2023). "Notably, from the PPI network, we observed that TNF, STAT3, TLR4, PIK3R1, and HSP90AB1 were significant targets for GAC intervention in CY-induced immunodeficiency." (PMID 37853057, 2023). "The indication for HCT in this cohort was cytopenia and/or malignancy and immunodeficiency, not responding to treatment with TNF inhibitors." (PMID 34324127, 2021). "The importance of CD4+ T cells, TNF-α, IFN-γ, IL-12p40, together with the IL-1/IL-1R1 pathway, in host resistance to intracellular Mtb infection is evident from animal models and human inherited and acquired immunodeficiencies." (PMID 32069329, 2020). "Although immunodeficiency may seriously affect host biomarker expression, IFN-γ and TNF-α in plasma from SLA-stimulated whole blood assay have been found useful for following up solid organ transplant recipients treated for VL." (PMID 29033933, 2017). "It has been reported that the TNF-α system was activated during HIV-1 and J subtype avian leukosis virus (ALV-J) infection and the raised level increased with disease progression and degree of immunodeficiency." (PMID 29312337, 2017). "It is unclear whether the immunodeficiency in patients observed in our study results solely from the production of anti-IFN-γ antibodies or it is worsening by the reduction of IL-2 and TNF-α production." (PMID 25329064, 2014). "Their reduced IL-2 produced by CD4 T cells, and their reduced TNF-α by both CD4 and CD8 cells may explain the immunodeficiency of such HIV− patients, in addition to the finding of autoantibodies to IFN-γ." (PMID 25329064, 2014). "Patients who present with hematological illness and immunodeficiency and who do not respond to TNF inhibitors may have the option to receive a hematopoietic stem cell transplant." (PMID 36606112, 2023). "Anti-TNF therapy does not, however, ameliorate marrow-failure or immunodeficiency." (PMID 35529868, 2022). "The cytopenias in DADA2 patients can be profound and refractory to treatment with TNF inhibitors and, unlike patients with severe immunodeficiencies, patients in our cohort specifically with neutropenia had difficulties successfully engrafting with transplantation." (PMID 35095905, 2021). "One hundred thirty-four patients (82.7%) were HIV-positive, 15 patients (9.3%) had immunosuppressant treatment (long-term steroids, anti-TNF and chemotherapy), and 13 patients (8%) were immunocompetent with no known immunodeficiency status at the time of diagnosis." (PMID 33194840, 2020). "HSCT may be an option in patients presenting with hematological disease and immunodeficiency not responding to TNF-inhibitors." (PMID 29951947, 2018). "It had been hypothesized that similar TNF-α levels in those with different types of AA give a clue toward the lack of immune reactions, while decreased TNF-α levels in the mild type may indicate a tendency for immunodeficiency in those with severe disease types." (PMID 37206670, 2023). "HCT is also a treatment option for patients who do not have access to anti-TNF agents even in the absence of immune cytopenia, BMF, or immunodeficiency." (PMID 34324127, 2021).
Immunodeficiency (continued). "Murine TNF-α, IL-1β, and IL-6 in the negative control group (NSG mice without AAV-PCSK9 injection) were below the ELISA detection threshold (1–5 pg/mL), consistent with NSG mice's severe immunodeficiency, which limits murine immune responses." (PMID 40237461, 2025).
leprosy (84 papers, 2006 to 2025). Leprosy is a chronic infectious disease affecting primarily the skin and peripheral nervous system. "Differences in leprosy outcomes are linked to polymorphisms in Th1-related genes such as TNF-α, IL-12, and TLR." (PMID 41306590, 2025). "TNF is able to regulate the expression of IL-6 and together enhance the inflammation process of nerve cells, causing neuritis in leprosy reactions." (PMID 38381878, 2024). "Corticosteroid use has been associated with an increased risk of leprosy, and anti-TNF use has been associated with a lower risk of leprosy when compared to corticosteroids." (PMID 38238209, 2024). "Certain studies have suggested that mutations in the TLR1 gene, which change the amount of IL-10 and tumor necrosis factor in macrophages, raise the risk of leprosy in Brazil and India." (PMID 38481606, 2023). "Herein, we assessed the circulating serum-sTREM-1 and TNF-α levels and their genetic polymorphisms in leprosy." (PMID 37457576, 2023). "In previous studies, TNF-α has been extensively described as an important proinflammatory cytokine associated with tissue damage in leprosy." (PMID 37457576, 2023). "TNFA genetic variants are classic risk factors for leprosy and its gene product, TNF, is a major signature cytokine for the tuberculoid pole." (PMID 36972292, 2023). "For example, polymorphisms in certain genes such as IL10, ninjurin 1 and TNF have been associated with leprosy susceptibility." (PMID 35492305, 2022). "Other study cited that the C allele is correlated with higher miR146-a and lower TNFα expression from nerve biopsies of leprosy patients." (PMID 34543271, 2021). "Non-invasive inflammatory biomarkers, such as C- reactive protein, erythrocyte sedimentation rate, leukocyte count, procalcitonin, interferon alpha, and tumor necrosis factor α (TNF-α) have been widely used to improve diagnostic accuracy of leprosy reactions." (PMID 32083213, 2020). "The tumor necrosis factor (TNF)–lymphotoxin-α (LTA) locus was found to be leprosy-associated by both linkage analysis and SNP scanning of this region." (PMID 32373110, 2020). "TNF-induced IL-8 can be produced by Schwann cells (SCs), indicating involvement of this factor in leprosy-associated nerve damage." (PMID 31017900, 2019). "It is suggested that LTB4 and LXA4 modulate the expression or the effects of TNF-α, a pro-inflammatory cytokine involved with the resistance/susceptibility to leprosy." (PMID 29472920, 2018). "Even to date, the resultsof candidate TNF (-308 G>A) gene based case–controlstudies are inconsistent in relation with leprosy risk." (PMID 28935761, 2017). "Recently, it has been reported that theminor A allele is related with low levels of TNF mRNA in peripheralblood total leukocytes of leprosy patients." (PMID 28935761, 2017). "Overall, the present study would greatly aid forcomprehensive understanding of the link between the TNF -308G>A polymorphism and leprosy risk globally." (PMID 28935761, 2017). "Despite many efforts, the molecular andbiological mechanism of interaction between the TNF genepolymorphism and risk of leprosy yet elucidated precisely." (PMID 28935761, 2017). "Independently, genome-wide association studies (GWAS) allowed the identification of genes and pathways playing a crucial role in leprosy susceptibility such as genes of the HLA system and genes in the TNF pathway." (PMID 28793313, 2017). "Research publicationseither showing TNFα gene polymorphism to predictsurvival in leprosy patients or considering leprosy variants as indicators forresponse to therapy were excluded straightaway." (PMID 28935761, 2017). "In this meta-analysis, we haveincluded 14 eligible case–control studies comprising 3327 cases and 3203healthy controls and analyzed the pooled ORs and P-value toappraise the precise association between the TNF -308 G>Apolymorphism and leprosy risk." (PMID 28935761, 2017).